NTRK3 (neurotrophic receptor tyrosine kinase 3)
Description:
Receptor tyrosine kinase involved in nervous system and probably heart development. Upon binding of its ligand NTF3/neurotrophin-3, NTRK3 autophosphorylates and activates different signaling pathways, including the phosphatidylinositol 3-kinase/AKT and the MAPK pathways, that control cell survival and differentiation.
Synonyms: TRKC; GP145-TrkC; gp145(trkC)
Tractability: Small molecule: an approved drug acts on it; a structure with a bound ligand is known; a high-quality ligand is known; it belongs to a druggable protein family. Antibody: its Gene Ontology location is reachable by antibodies, with high confidence; UniProt predicts a signal peptide or a membrane-spanning region. PROTAC: it is named in the literature on targeted protein degradation; its protein half-life has been measured; a small molecule that binds it is known. Other modalities: an approved drug acts on it.
Target class: Protein Kinase; Tyrosine protein kinase Trk family; TK protein kinase group; Enzyme; Kinase
Chemical probes: D2202-1 (high quality), GNF-5837 (high quality), larotrectinib (high quality)
Gene: Protein-coding gene on chromosome 15 (87,859,751 to 88,256,993, reverse strand). Ensembl gene ENSG00000140538.
Subcellular location: Membrane
Subcellular location (Human Protein Atlas): Nucleoli; Nucleoli rim; Nuclear membrane
Pathways (Reactome):
Signal Transduction: Activated NTRK3 signals through PI3K; Activated NTRK3 signals through PLCG1; Activated NTRK3 signals through RAS; NTF3 activates NTRK3 signaling; NTRK3 as a dependence receptor; PI5P, PP2A and IER3 Regulate PI3K/AKT Signaling; PIP3 activates AKT signaling; Signaling by NTRK3 (TRKC)
Disease: Constitutive Signaling by Aberrant PI3K in Cancer
Neuronal System: Receptor-type tyrosine-protein phosphatases
Gene Ontology:
Molecular function: neurotrophin receptor activity; protein binding; neurotrophin binding; transmembrane receptor protein tyrosine kinase activity; ATP binding; protein kinase activity; protein tyrosine kinase activity
Biological process: cell surface receptor protein tyrosine kinase signaling pathway; heart development; positive regulation of cell migration; positive regulation of cell population proliferation; positive regulation of gene expression; positive regulation of MAPK cascade; positive regulation of phosphatidylinositol 3-kinase/protein kinase B signal transduction; positive regulation of positive chemotaxis; cellular response to nerve growth factor stimulus; positive regulation of neuron projection development; animal organ development; cell communication; circadian rhythm; neurotrophin signaling pathway; system development
Cellular component: nucleolus; receptor complex; axon; plasma membrane; cytoplasm; membrane
Genetic constraint (gnomAD): Loss-of-function variants: 23 observed, 93.78 expected, observed/expected ratio (o/e) 0.25, 90% interval 0.17 to 0.35. The upper end of that interval is the gene's LOEUF score, 0.35, which puts it in group 1 of 6, group 1 being the genes least tolerant of losing a copy. Missense variants: 877 observed, 1,117.6 expected, observed/expected ratio (o/e) 0.78, 90% interval 0.74 to 0.83. Synonymous variants: 483 observed, 423.97 expected, observed/expected ratio (o/e) 1.14, 90% interval 1.06 to 1.23.
Gene-disease validity (ClinGen):
ClinGen rates the evidence that NTRK3 causes each of these diseases.
congenital heart disease (autosomal dominant): Disputed. A heart disease that is present at birth.
Cancer hallmarks: invasion and metastasis (promotes); escaping programmed cell death (promotes); escaping programmed cell death (suppresses); proliferative signalling (promotes)
Homologues: Orthologues: chimpanzee NTRK3 (99% identical), pig NTRK3 (99% identical), dog NTRK3 (98% identical), guinea pig NTRK3 (98% identical), macaque NTRK3 (98% identical), rat Ntrk3 (97% identical), mouse Ntrk3 (96% identical), tropical clawed frog ntrk3 (83% identical), zebrafish ntrk3a (73% identical), zebrafish ntrk3b (70% identical). Paralogues in human: NTRK2 (53% identical), NTRK1 (49% identical), ROS1 (28% identical), MUSK (26% identical), INSR (25% identical), IGF1R (24% identical), INSRR (24% identical), ROR2 (23% identical), ROR1 (23% identical), ALK (21% identical), TIE1 (21% identical), DDR2 (20% identical), and 41 more.
Diseases named in the same sentence as NTRK3 in open-access papers:
NTRK3 is named in the same sentence as 251 diseases in open-access papers, as found by Europe PMC text mining. Sharing a sentence is not in itself a finding about the gene and the disease. The quoted sentences say what the papers report.
fibrosarcoma (50 papers, 2005 to 2026). A malignant mesenchymal fibroblastic neoplasm affecting the soft tissue and bone. "Adult fibrosarcoma is marked by chromosomal instability, often presenting with aneuploidy and recurrent NTRK3 gene fusions (STRN1-NTRK3 or STRN3-NTRK3), which are actionable targets for tyrosine kinase inhibitors." (PMID 40917595, 2025). "A majority of infantile fibrosarcomas (IF, sny: congenital fibrosarcoma) are associated with ETV6::NTRK3 (TrkC) translocations, while in rarer cases, related translocations involving NTRK1,-2, and, -3 with different fusion partners have been identified." (PMID 38611033, 2024). "While ETV6::NTRK3 is a well-established genetic driver of infantile fibrosarcoma, other fusions of NTRK1/3 and various other kinase genes including MET, RET, RAF1, or BRAF have been implicated in the pathogenesis of these tumors." (PMID 38217715, 2024). "Despite a variable morphological spectrum, infantile fibrosarcoma belongs to the NTRK3-rearranged family of tumors." (PMID 37238376, 2023). "Among them, tumors resembling lipofibromatosis or malignant peripheral nerve sheath tumors often harbor intra-chromosomal NTRK1 rearrangements, while most infantile fibrosarcomas are characterized by canonical ETV6::NTRK3 fusions." (PMID 36801905, 2023). "The ETV6::NTRK3 fusion represents the canonical fusion (90% frequency) for both infantile fibrosarcoma and mammary analog secretory carcinoma, while being detected at a much lower frequency (5–10%) in a variety of other cancers of various lineages." (PMID 36801905, 2023). "The second patient underwent open biopsy also with histopathological diagnosis of fibrosarcoma and the same mutation in the TRK gene ( NTRK3 )." (PMID 35761904, 2022). "Among sarcomas, infantile fibrosarcomas show fusions of the NTRK3 gene in more than 90% of the cases." (PMID 35645621, 2022). "Over 80% of infantile fibrosarcomas and secretory carcinomas of the breast and salivary glands have NTRK3 fusions, usually ETV6-NTRK3, which is pathognomonic in these rare pediatric and adult cancers." (PMID 34531526, 2022). "Another series presented two NTRK3 fused fibrosarcoma-like spindle cell tumors of the extremities, one of which was located in the bone." (PMID 33803146, 2021). "Nevertheless, NTRK fusions also drive the great majority of certain specific rare neoplasms, for example, infantile fibrosarcoma, cellular, mixed congenital mesoblastic nephroma, and secretory carcinoma of the breast and salivary glands with NTRK3 fusions." (PMID 33996597, 2021). "While ETV6- NTRK3 fusion is common in infantile fibrosarcoma, NTRK1/3 fusion in pediatric tumors is scarce and, consequently, not well known." (PMID 32957984, 2020). "ETV6::NTRK3 fusion has been identified in not only infantile mesenchymal neoplasms, such as infantile fibrosarcoma/congenital “cellular” mesoblastic nephroma and secretory carcinomas of the breast, salivary gland, skin, but also in thyroid cancers associated with a history of radiation." (PMID 38390852, 2024). "FISH detection of ETV6::NTRK3 is sufficient to confirm the diagnosis of infantile fibrosarcoma." (PMID 38217715, 2024). "The first category of NTRK3 fused tumors includes high-grade infantile fibrosarcoma-like tumors." (PMID 33803146, 2021). "Three cases harbored fusions between EML4 and NTRK3, first observed in infantile fibrosarcoma." (PMID 33441414, 2021). "Mesoblastic nephroma, shares an identical fusion marker (TV6- NTRK3) with congenital fibrosarcoma." (PMID 16092965, 2005). "However, when ETV6–NTRK3 fusion is expected (e.g., in mammary gland secretory carcinoma, salivary gland secretory carcinoma, and infantile fibrosarcoma), NTRK3 alone needs to be examined and only a single test is required for the examination, the use of FISH is appropriate." (PMID 37212982, 2023). "The NTRK gene and fusion partner was TPM3::NTRK1 (fibrosarcoma), LPPR1::NTRK2 (Ewing’s sarcoma), DAB2IP::NTRK2 (primitive neuroectodermal tumor), and RAD51B::NTRK3 (PTC)." (PMID 38967220, 2024).
fibrosarcoma (continued). "Among pediatrics there was one case each of fibrosarcoma (TPM3::NTRK1), Ewing’s sarcoma (LPPR1::NTRK2), primitive neuroectodermal tumor (DAB2IP::NTRK2), and papillary thyroid carcinoma (RAD51B::NTRK3)." (PMID 38967220, 2024). "Echinoderm Microtubule Associated Protein like-4 (EML4)-NTRK3 fusion has also been identified in infantile fibrosarcomas and congenital mesoblastic nephroma, in addition to ETV6-NTRK3 fusion." (PMID 32957984, 2020). "One other target NTRK3 is the transcription factor component of common translocation fusion protein, ETV6-NTRK3, which occurs commonly in congenital (infantile) fibrosarcoma and cellular mesoblastic nephroma." (PMID 20718987, 2010). "Infantile Fibrosarcoma is a malignant tumor of fibroblastic origin, typically found in early childhood, locally aggressive, and characterized by molecular alterations that activate tyrosine kinase signaling, primarily the ETV6::NTRK3 fusion." (PMID 39940949, 2025). "In a minority of cases, NTRK3-negative infantile fibrosarcomas have been documented to exhibit NTRK1 gene rearrangements instead." (PMID 38397049, 2024). "One of the typical pediatric tumors, Infantile Fibrosarcoma (IFS), is a malignant tumor of fibroblastic origin, typically found in early childhood, locally very aggressive, and characterized by molecular alterations that activate tyrosine kinase signaling, primarily the ETV6::NTRK3 fusion." (PMID 39940949, 2025). "Similarly, EGFR ITDs are described in the setting of infantile fibrosarcoma and congenital mesoblastic nephroma, particularly in classic or mixed subtype, and aids in diagnostics if the tumor is negative for the more commonly identified ETV6::NTRK3 fusion." (PMID 37686670, 2023).
neuroblastoma (40 papers, 1996 to 2026). Neuroblastoma (NB) is the most common solid, extracranial childhood tumor. "Specifically, TrkA (NTRK1) and C (NTRK3) expression are associated with favorable outcomes in neuroblastoma, while TrkB (NTRK2) is associated with biologically aggressive disease." (PMID 29207623, 2017). "It was reported that NTRK3 works with microRNAs to control proliferation of human neuroblastoma cells and NTRK3 also is a susceptibility factor for Anxiety Disorders after interplaying with microRNAs." (PMID 27351280, 2016). "In particular, we show that the overexpression of miR-128 - a brain enriched miRNA - causes morphological changes in SH-SY5Y neuroblastoma cells similar to those observed using an siRNA specifically directed against truncated NTRK3, as well as a significant increase in cell number." (PMID 21143953, 2010). "SH-SY5Y neuroblastoma cells were used to investigate whether miRNAs causing a significant decrease in luciferase activity were also able to downregulate endogenous NTRK3." (PMID 21143953, 2010). "Conversely, NTRK3 expression was a good prognosis factor in a variety of cancers and more specifically in melanomas, neuroblastomas, and colorectal cancer." (PMID 35141152, 2021). "Gene fusions, as well as the overexpression of NTRK3, have also been identified as potential contributors to certain cancers, including medulloblastoma, neuroblastoma, and melanoma." (PMID 29617282, 2018). "It was shown, that the complete and truncated isoforms of NTRK3 in neuroblastoma cells can be regulated by distinct microRNAs in the isoform-specific manner." (PMID 28984201, 2017). "It was also found that miR-151-3p represses the full-length isoform of human neurotrophin-3 receptor gene NTRK3 in neuroblastoma cells." (PMID 27930738, 2016). "This is the case for example of NTRK3, which is highly expressed in neuroblastomas with good prognosis and highly correlates with patient survival." (PMID 21143953, 2010). "Neurotrophic receptor tyrosine kinase 3 (NTRK3) has pleiotropic functions: it acts not only as an oncogene in breast and gastric cancers but also as a dependence receptor in tumor suppressor genes in colon cancer and neuroblastomas." (PMID 38593276, 2024). "Of potential therapeutic relevance, we identified an NTRK3-SLMAP fusion in a neuroblastoma patient." (PMID 35585047, 2022). "However, some studies show that NTRK3 is a potential tumor suppressor gene in colorectal cancer and is also highly expressed in good-prognosis neuroblastomas as well as medulloblastomas, but NTRK3 works as a oncogene in breast tumor." (PMID 27351280, 2016). "A similar role for NTRK3 in neuroblastomas has recently been shown." (PMID 23874207, 2013). "In addition, the direct targeting of mir-185-5p to NTRK3 has been demonstrated in neuroblastoma." (PMID 27916857, 2016). "However, NTRK3 has also been shown to be a tumor suppressor gene in neuroblastomas." (PMID 23874207, 2013). "We surveyed our seven neuroblastoma cell lines for NTRK1,2,3 expression and demonstrated enhanced mRNA levels for NTRK2 and NTRK3 in all tested cell lines, as well as enhanced NTRK1 expression in 5 of 7 experimental cell lines." (PMID 29207623, 2017). "Neuroblastoma tumorigenesis is closely related to the expression of the neurotrophins and their specific receptors, the Trk family; TrkA, TrkB and TrkC (also known as NTRK1, NTRK2, and NTRK3, respectively)." (PMID 36831211, 2023). "In the presence of NT-3, NTRK3 induces differentiation, guidance or survival in neurons; however, NTRK3 can alternatively induce apoptotic cell death in the absence of NT-3 in neuroblastoma cells and presumably other cell types." (PMID 23874207, 2013).
breast carcinoma (36 papers, 2008 to 2025). "ETV6-NTRK3, which had been identified as a causative fusion oncogene in over 90% of secretary breast cancer samples, encodes a dimerization domain of the ETV6 transcription factor, conjoined to kinase domain of NTRK3." (PMID 29414922, 2018). "One of the breast carcinoma samples tested exhibited a fusion in the neurotrophic receptor tyrosine kinase 3 (NTRK3) gene." (PMID 38800398, 2024). "Analysis of rare missense variants identified evidence of associations of TMEM161A, SIPA1L1, and ERCC2 with overall breast cancer, RNF175 and NCKAP1L with ER-positive disease, and SLC22A10, PHAX, SMARCA2, EML5, NTRK3, and MED23 with ER-negative disease." (PMID 35884425, 2022). "When missense variants were assessed, three further associations were observed for overall breast cancer (TMEM161A, SIPA1L1, ERCC2), and a further seven were observed for subtypes (RNF175, NCKAP1L, PHAX, SMARCA2, EML5, NTRK3, MED23)." (PMID 35884425, 2022). "who reported that NTRK3 significantly enhanced the capability of breast cancer cells to bring about primary tumor formation and pulmonary metastases." (PMID 33575204, 2020). "Our findings are in contrast to other studies in breast cancer that have demonstrated that NTRK3 is oncogenic." (PMID 23874207, 2013). "NTRK3 has been previously shown to be an oncogene in breast cancer and possibly hepatocellular carcinoma." (PMID 23874207, 2013). "The identification of methylated NTRK3 in CRC was unexpected given that NTRK3 has been shown to be an oncogene in breast cancer and possibly hepatocellular carcinoma." (PMID 23874207, 2013). "However, owing to the limited number of studies about NTRK3 and cancer, we aimed to investigate NTRK3 as a potential prognostic marker for breast cancer (BC)." (PMID 40142285, 2025). "NTRK3 has been classified as an oncogene in breast cancer and gastric cancer." (PMID 38593276, 2024). "Evidence suggests that NTRK3 is not only essential for the development of the nervous system but also plays a critical role in the progression of numerous cancer types, including gastric, thyroid, lung, glial, and breast cancers." (PMID 38593276, 2024). "This included 7 breast cancer-related genes: caspase 8 (CASP8), cadherin 1 type 1 (CDH1), estrogen receptor 1 (ESR1), ETS variant 6 (ETV6), forkhead box A1 (FOXA1), GATA-binding protein 3 (GATA3) and neurotrophic tyrosine kinase receptor type 3 (NTRK3)." (PMID 31182966, 2019). "In addition, overexpression of NTRK3, EPHA7, and FGFR2 (M subtype-specific TK genes) has been linked to a worse prognosis in breast cancer and could promote TNBC formation." (PMID 36672350, 2023). "Among the six fusions identified in breast carcinoma samples of the 38 samples examined, three involved NOTCH2, and one each involved FGFR3, NTRK3, and BRAF." (PMID 38800398, 2024). "The best putative candidates in this group were TMEM161A, ERCC2, and SIPA1L1 for overall breast cancer, RNF175 and NCKAP1L for ER-positive disease, and PHAX, SMARCA2, NTRK3, EML5, and MED23 for ER-negative disease." (PMID 35884425, 2022). "NTRK3 has a critical role in secretory breast cancer gene, with the EVT6‐NTRK3 fusion oncogene being considered a primary initiating event." (PMID 34766125, 2020). "Only neurotrophic tyrosine kinase receptor type 3 (NTRK3; 5.76-fold downregulation) and ETV6 (0.64-fold downregulation) were related to breast cancer." (PMID 31182966, 2019). "However, NTRK3 has also been found in several nonneural cell types diseases (medullary thyroid carcinoma, breast cancer, colon cancer, lung cancer, liver cancer, prostate cancer) and may also play a crucial role in the initiation, progression, and migration of many tumors in human." (PMID 27351280, 2016).